MMP1 (matrix metallopeptidase 1)
Diseases named in the same sentence as MMP1 in open-access papers (continued):
Sharing a sentence is not in itself a finding about the gene and the disease.
oro-pharyngeal tumours (1 paper, 2017). "The pronounced expression and activity of MMP1, 2, 9 and 14 in oro-pharyngeal tumours and in the invasive E6/E7-HFK indicates that MMPs have a significant role in invasion." (PMID 26001294, 2017).
osteitis (1 paper, 2019). "Cigarette smoking was associated with the up-regulation of MMP-1 and MMP-9 in the nasal tissues of patients with airway inflammatory diseases, and with AE osteitis, and with therapeutic resistence." (PMID 31653934, 2019).
ovarian tumors (1 paper, 2021). "EVs derived from ovarian cell lines and primary ovarian tumors deliver mRNA encoding matrix metallopeptidase 1 (MMP1) which can degrade extracellular matrix components and induce activation of Caspase 1 thus triggering apoptosis in receiving cells." (PMID 34572444, 2021).
pelvic organ prolapse (1 paper, 2013). Abnormal descent of a pelvic organ resulting in the protrusion of the organ beyond its normal anatomical confines. "We speculated that similar mechanisms related to the 1G/2G MMP-1 and 5A/6A MMP-3 SNPs might exist within the pelvic floor connective tissue in women with clinically significant pelvic organ prolapse." (PMID 23108733, 2013).
phlebitis (1 paper, 2021). Inflammation of a vein. "MMP1 expression in turn drives the extracellular matrix degradation and remodeling around blood vessels thereby promoting leukocyte adhesion and emigration into the perivascular space, eventually resulting in phlebitis frequently observed in the earlier stages of Wooden Breast." (PMID 33395447, 2021).
Pleuritis (1 paper, 2018). Inflammation of the pleura. "MMP-1, − 2, − 8 and − 9 were found to be elevated in pleural fluid of patients with TB compared to pleural fluid of non-TB pleuritis." (PMID 30045688, 2018).
pulmonary stenosis (1 paper, 2025). "In the additional GEE model adjusting for either RV dilation or pulmonary stenosis (see Online Supplement), MMP1, PIIINP, and elevated PICP remained significantly associated with worse RVLS." (PMID 41144173, 2025).
pyometra (1 paper, 2015). "SLPI, PTGS2/COX2, MMP1, S100A8, S100A9 and IL8 were among the top up-regulated genes detected in pyometra, further confirmed by external expression data." (PMID 26222498, 2015).
radicular cysts (1 paper, 2017). "Previous studies have shown the presence and immunolocalization of MMP-1 and TIMP-1 in human radicular cysts." (PMID 29054963, 2017).
retinal angioma (1 paper, 2009). "We observed that variants of MMP1 and MMP3 were significant modifiers of RCC risk (and risks of retinal angioma and cerebellar haemangioblastoma) in VHL disease patients." (PMID 19551141, 2009). "Our findings suggest that functional SNPs in MMP1/MMP3 can influence susceptibility to RCC in familial (VHL disease) and sporadic patients and that MMP1 rs1799750 and MMP3 rs679620 genotypes can also influence the risk of retinal angioma and cerebellar haemangioblastoma in VHL disease." (PMID 19551141, 2009). "In addition, the observation that MMP1 and MMP3 genotypes also appeared to influence retinal angioma and cerebellar haemangioblastoma risks is consistent with our previous report suggesting shared genetic modifiers of retinal angiomatosis, cerebellar haemangioblastomas and RCC risks in VHL disease." (PMID 19551141, 2009).
retinal vein occlusion (1 paper, 2020). An occlusion of the retinal vein. "The AH concentrations of MMP-1, MMP-2, MMP-7, and MMP-9 are also elevated in patients with retinal vein occlusion." (PMID 32596291, 2020).
retinoblastoma (1 paper, 2019). A malignant tumor that originates in the nuclear layer of the retina. "The results confirm that MMP-1, MMP-2, MMP-9, and VEGF overexpression is highly related to poor retinoblastoma differentiation and tumor invasion." (PMID 31311559, 2019). "MMP-1, MMP-2, MMP-9 and VEGF play important roles in the development and progression of retinoblastoma." (PMID 31311559, 2019). "We concluded that the overexpression of MMP-1, MMP-2, MMP-9 and VEGF is highly related to poor retinoblastoma differentiation, tumor invasion and advanced clinical stage and, thus, have a role in predicting the prognosis of retinoblastoma patients." (PMID 31311559, 2019).
schistosomiasis (1 paper, 2023). An infectious disease caused by parasitic trematodes of the genus Schistosoma that colonize human blood vessels and release eggs that can cause granulomatous reactions leading to acute (swimmer's itch or acute schistosomiasis syndrome) or chronic disease. "Ceramide generated by nSMase or exogenously added ceramide analogs have been reported to potently activate the expression of the fibroblast’s MMP-1 (Collagenase-1) that degrades collagens types I, II, and III, the predominant collagen isotypes associated with egg granuloma in schistosomiasis." (PMID 38039267, 2023).
small cell carcinoma (1 paper, 2008). A neuroendocrine carcinoma composed of small malignant cells which are often said to resemble "oat cells" under the microscope. "In the stratified analysis by histological types, we observed that homozygotes for variant allele of polymorphisms in MMP1 and MMP13 genes increase the risk of developing small cell carcinoma." (PMID 19094243, 2008).
subarachnoid hemorrhage (1 paper, 2016). A serious neurological disorder characterized by intracranial hemorrhage into the subarachnoid space. "We examined multiple clinical parameters, such as age, sex, family history of ICAs or subarachnoid hemorrhage (SAH), serum creatinine level and the presence or absence of dialysis therapy, in addition to the serum MMP1 levels." (PMID 27418197, 2016).
teratocarcinoma (1 paper, 2010). A germ cell tumor characterized by the presence of an embryonal carcinoma component and a teratoma component. "The highest expression was detected for MMP-1 on mRNA level in the teratocarcinoma cell line PA-1 but no corresponding protein expression could be detected by Western blot analysis." (PMID 20942921, 2010).
thyroid gland disorder (1 paper, 2022). A disease involving the thyroid gland. "MMP1 expression was significantly associated with gender (P=0.029), T stage (P =0.004), N stage (P =0.005), extrathyroidal extension (P =0.025), histological type (P <0.001) and the thyroid gland disorder history (P <0.001)." (PMID 36479070, 2022).
Trichiasis (1 paper, 2019). Inversion and rubbing of the eyelashes against the globe of the eye. "Furthermore, doxycycline treatmentin vitro reduced MMP1, 9 and 12 expression by primary fibroblasts from trichiasis patients and reduced collagen matrix contraction." (PMID 37426632, 2019).
tuberculous meningitis (1 paper, 2017). "We have previously reported compartmentalized inflammatory responses in HIV-infected patients with tuberculous meningitis (TBM), in cerebrospinal fluid (CSF) and plasma, with elevated CSF MMP-1, -7, and -10 in TBM-IRIS compared with non-IRIS controls, although MMP-8 was not studied." (PMID 28475709, 2017).
urolithiasis (1 paper, 2023). Stone(s) within the urinary tract. "For LASSO regression analysis, six variables, MMP1, MMP3, MMP9, MMP10, MMP27 and, MMP28, were screened as diagnostic markers for urolithiasis." (PMID 37006258, 2023). "Subsequently, we extracted DMMMPs and genes in urolithiasis-related modules for intersection and found MMP1, MMP3, MMP9, MMP12 were in the royalblue module and MMP10 were in the green module, suggesting all of DEMMPs might be implicated in RPs and urolithiasis." (PMID 37006258, 2023).
viral myocarditis (1 paper, 2021). Myocarditis that is caused by an infection with a viral agent. "Subsequently, we learned intermolecular interactions of herbal components and their targeting heart-tissue-specific CHRM2, FABP3, TNNC1, TNNI3, TNNT2, and SCN5A and cardiac-myocytes-specific IL6, MMP1, and PLAT coupled with viral myocarditis." (PMID 34456633, 2021).
vitamin D insufficiency (1 paper, 2023). "Patients with sufficient vitamin D levels had lower MMP-1 and MMP-13 levels compared to patients with vitamin D insufficiency (p < 0.001 and p < 0.001, respectively)." (PMID 36845046, 2023).
tumor (834 papers, 1992 to 2026). "Clinical validation revealed a preliminary association between tumor stiffness and MMP1 expression in CC tissues, offering a new perspective for risk stratification and clinical evaluation in this malignancy." (PMID 42318471, 2026). "In the animal model, the overt expression of MMP-1 was associated with the empowerment of the primary tumor to spontaneously metastasize to the other organ." (PMID 40943127, 2025). "As the prototypical member, MMP1 has been extensively implicated in tumor cell invasion and metastasis due to its dysregulated expression." (PMID 40666104, 2025). "High MMP1 expression was associated with increased activity in epithelial–mesenchymal transition signaling and TNFα/NF-κB pathways, which are known to promote tumor progression." (PMID 40394037, 2025). "High expression of RUNX2 in RCC patients is associated with higher tumor grade, stage, and poorer survival and correlates positively with MMP1 expression level." (PMID 40386045, 2025). "First, we uncovered a novel and previously unidentified association among SPHK1, MMP1, and PD-L1, all of which are crucial molecules in tumor initiation and progression, particularly in highly immunogenic HNSCC." (PMID 39629135, 2024). "The participation of MMP-1 in tumor progression is largely associated with its ability to degrade fibrillar collagens, as well as with regulating the Th1/Th2 inflammatory response." (PMID 39769318, 2024). "Previous studies showed that MMP-1 is overexpressed in several human cancers, and is associated with invasive behavior and tumor progression." (PMID 38321552, 2024). "The matrix metalloproteinase 1 encoded by the MMP1 gene plays a role in tumour invasion and metastasis." (PMID 39120548, 2024). "MMP1 is known to be overexpressed in various cancer types and associated with both tumor development and metastasis and, intriguingly, surfaced as a defensive element against CRC." (PMID 39011483, 2024). "MMP-1 expression has been linked to increased cell proliferation, tumor development, metastasis, and resistance to chemotherapy in various tumors." (PMID 37397367, 2023). "Previous research has suggested that differential glycosylation of EMMPRIN exhibits functional relevance in tumour cells, with the highly glycosylated form being associated with enhanced cell adhesion, cell migration, and MMP-1 and MMP-2 production." (PMID 37174066, 2023). "MMP1, a secreted enzyme that cleaves fibrillar collagen, has been linked to cancer by promoting cancer cell proliferation, tumor angiogenesis, and vasculogenesis." (PMID 36874118, 2023). "A significant association was found between increased MMP1 expression and tumor size, grade, pathological T stage, and perineural invasion." (PMID 35806108, 2022). "Many studies have proved that MMP1 is associated with tumor progression in different kinds of cancers." (PMID 35426219, 2022). "All the findings indicated an underlying mechanism of MMP1 expression in remodulating the tumor-immune microenvironment and immune escape." (PMID 35948625, 2022). "The study demonstrated that high MMP-1 expression is significantly associated with high-grade tumour stages and suggests a more aggressive tumour phenotype." (PMID 35204653, 2022). "In the relationship between MMP1 expression and estimate score, MMP1 expression was significantly associated with estimate score in 22 tumor types." (PMID 36727076, 2022). "The positive association between CD26 and MMP1 suggests that MMP1 is involved in CD26-induced tumor progression effects in CRC cells." (PMID 35163100, 2022). "This study showed for the first time the association of CD26+ cells with tumor angiogenesis and its regulatory effect on MMP1 expression." (PMID 35163100, 2022). "The objective of our study was to examine the expression of tumor-progression-associated MMPs (MMP-1, MMP-2, and MMP-9) and tissue inhibitors of metalloproteinases (TIMP-1 and TIMP-2) in locally invasive PTC and their relation to clinicopathological features." (PMID 36551933, 2022).
tumor (continued). "Meanwhile, matrix metalloproteinases also play an essential role in many tumors, high expression of MMP1 were closely associated with tumor metastasis." (PMID 33816248, 2021). "The decreased FoxO3a expression in tumour cells was reported to be associated with decreased MMP1, MMP9 and MMP13 levels and inhibited invasion and migration." (PMID 33811439, 2021). "The high expression of MMP-1 in the tumor stroma induces structural changes at the tumor periphery, with a loss of the palisading arrangement, which suggests a poor differentiation and a histological aspect that is correlated with an unfavorable prognosis." (PMID 34204372, 2021). "DDR1 is associated with tumor progression and is linked to regulating cell adhesion and migration via modulating the expression of MMPs like MMP1, MMP2, and MMP937,38." (PMID 34837026, 2021). "In contrast, overexpression of MMP1 has been reported in different cancer types, making a path in the tumor‐associated microenvironment and contributing to cancer cell invasion." (PMID 34121340, 2021). "Levels of MMPs, such as MMP1, 2 and 9, have been found to be increased in GC, and their overexpression has been shown to be associated with tumor invasion and metastasis." (PMID 32863948, 2020). "Our results showed that loss of miR-202-3p induce MMP-1 in BC cells and disrupts the brain endothelial integrity to promote tumor cells transmigration through the brain endothelium." (PMID 33002044, 2020). "It is not known if downregulated miR-330-5p is associated with enhanced MMP1 expression in OAC tumours although silencing miR-330-5p in vivo enhanced tumour growth." (PMID 31391080, 2019). "Polymorphisms in promoter regions of MMP3 and MMP1, and particularly the MMP1 -1607 1G>2G polymorphism, are risk factors for tumor development and progression." (PMID 30781344, 2019). "According to one study, MMP-1 is associated with various specific pathological states, including inflammation, immunity, tumor invasion, and metastasis." (PMID 30886066, 2019). "Coexpression of Nact and lgl-IR results in massive tumor overgrowth and displays hallmarks of cancer, such as MMP1 upregulation and loss of epithelial integrity." (PMID 29661224, 2018). "Supporting these findings in vivo, data from their tumor models showed that overexpression of chemerin was associated with reduced tumor MMP-1 and p-Akt levels, elevated PTEN levels, and reduced metastases." (PMID 30555465, 2018). "Matrix metalloproteinase-1 (MMP1) is a member of the matrix metalloproteinases family, and its aberrant expression is implicated in tumor invasion and metastasis." (PMID 29207651, 2017). "A plenty of studies indicated that MMP1 is implicated in the progression and metastasis of tumor cells." (PMID 29207651, 2017). "Among the various MMPs, MMP1 is the most ubiquitously expressed one and its overexpression is associated with several specific pathological status, including inflammation, tumor invasion and metastasis." (PMID 28612708, 2017). "MMP-1 is also upregulated in tumor tissues and has been suggested to be associated with tumor invasion and metastasis." (PMID 28496473, 2017). "BSG (CD147, EMMPRIN) is an inducer of tumor cell associated MMPs, including MMP1, MMP2, MMP3, and MMP9." (PMID 26769849, 2016). "Expression of MMP-1 is reported to be associated with the initial steps of tumor growth in cutaneous SCC." (PMID 27271600, 2016). "In multivariate analysis, CTC_EMT and tumor grade were independently associated with MMP1 expression in cancer cells, while CTC_EMT and Ki67 were independently associated with MMP1 expression in cancer associated stroma." (PMID 24972610, 2014). "MMP-1 was considered to be closely associated with tumor aggressiveness, metastatic potential and poor prognosis." (PMID 25109342, 2014). "Alternately, tumor-derived MMP-1 and -2 were associated with a prolonged survival, with MMP-1 being a prognostic factor in both the univarate and multivariate survival analysis." (PMID 25483099, 2014).
tumor (continued). "The overexpression of MMP1 has been shown in tumor tissues and has been suggested to be associated with tumor invasion and metastasis." (PMID 24883044, 2014). "In conclusion, in this prospective translational study, we for the first time showed association between CTC_EMT and expression MMP1 in primary tumor tissue." (PMID 24972610, 2014). "MMPs, and MMP1 specifically, have been studied using indicators of metastatic potential by evaluating tumor stage at time of diagnosis, tumor grade and histology and been shown to be associated with greater metastatic potential." (PMID 25541970, 2014). "In univariate long-rank analysis, tumor size (P = 0.000), status of nodal involvement (P = 0.000), tumor stage (P = 0.000), and stromal MMP-1 expression (P = 0.047) were significantly associated with overall survival." (PMID 25510449, 2014). "Patients with CTC_EMT in peripheral blood had significantly increased expression of MMP1 in tumor cells (p = 0.02) and tumor associated stroma (p = 0.05) than those of patients without CTC_EMT." (PMID 24972610, 2014). "MMP-1 is the most ubiquitously expressed interstitial collagenase and its overexpression is associated with several pathological conditions, including tumor invasion and metastasis." (PMID 24505369, 2014). "While only MMP1 was associated with tumor differentiation, MMP3 and MMP9 were associated with ER−/PR− tumors." (PMID 23696797, 2013). "All these data reveal that high MMP-1 positivity in both stromal and tumor cells was significantly associated with tumor evolution, poor prognosis and shortened survival." (PMID 21834986, 2011). "In our study, MMP-1 expression in tumour cells and in stromal cells showed a significant association with tumour grade." (PMID 21835023, 2011). "The induction of MMP-1 is well in line with the activation of the tumor progression-associated transcription factors NFκB and AP-1, which are induced upon artesunate treatment as evidenced here by EMSA analyses." (PMID 21637790, 2011). "We found that MMP-1 positivity in tumour cells with a 70% cut-off level had a significant association with survival in univariate analyses." (PMID 21835023, 2011). "MMP-13 is another tumor-derived MMP that is implicated to have cooperative effects with MMP-1 and is related to cancer aggressiveness." (PMID 20946664, 2010). "The results demonstrate that MMP1 silencing was associated with a trend of decreased rate of pulmonary metastasis but also increases in primary tumor volume and vascularization." (PMID 21170377, 2010). "In this context, we note that pathogenesis of bronchial cancer is also linked to extracellular-matrix–degrading properties of MMP-1, which includes tumor cell growth, invasion, and metastatic capability." (PMID 19337515, 2009). "Previous studies in tumor cell lines showed that an over-representation of the G allele of this promoter SNP resulted in increased MMP1 transcriptional activity, hence more aggressive matrix degradation." (PMID 18439317, 2008). "The gene encoding this factor is coexpressed with the genes encoding uPA (urokinase type plasminogen activator) and MMP-1 (matrix metalloproteinase-1) in various types of tumor." (PMID 18958307, 2008). "Notably, the gene set associated with high MMP1 expression was linked to poor prognosis across multiple tumor types." (PMID 40394037, 2025). "MMP1: Although MMPs are classically associated with extracellular matrix remodeling, our single-cell analysis revealed malignant cell-specific MMP1 enrichment, implicating tumor-intrinsic signaling in metastasis beyond stromal interactions." (PMID 41472745, 2025). "Finally, the robust association with MMP–1 underscores the importance of active extracellular matrix degradation, a fundamental step for tumor cell invasion." (PMID 41194922, 2025).